GLI2 (GLI family zinc finger 2)
Diseases named in the same sentence as GLI2 in open-access papers (continued):
Sharing a sentence is not in itself a finding about the gene and the disease.
CNS tumor (1 paper, 2016). "Prior work showed that both Gli1 and Gli2 proteins were Class I HDAC targets in CNS tumor progenitor cells, and that de-acetylation promoted their transcriptional activities." (PMID 27668865, 2016).
neurological disorders (1 paper, 2026). "In relation to this, GLI2 mediates Sonic Hedgehog signaling, neurological disorders, and bone formation." (PMID 41246799, 2026).
GLI2 also shares sentences with these, for which no sentence is quoted: non-small cell lung carcinoma (4 papers); acne (3); acute monocytic leukemia (3); cryptorchidism (3); Micropenis (3); 22q11.2 deletion syndrome (2); anal stenosis (2); anorectal malformation (2); benign tumors (2); breast tumors (2); congenital insufficiency of the aortic valve (2); cystic kidney disease (2); esophageal squamous cell carcinoma (2); head and neck carcinoma (2); hepatoblastoma (2); hypogonadotropic hypogonadism (2); idiopathic pulmonary fibrosis (2); Insulin resistance (2); myeloid leukemia (2); myeloid malignancies (2); rhabdomyosarcoma (2); skin cancer (2); androgen alopecia (1); Anophthalmia (1); Aortic valve disease (1); apical periodontitis (1); atopic dermatitis (1); autosomal dominant disease (1); biliary atresia (1); bladder (1).
A further 72 diseases each share a sentence with GLI2 in 1 paper.